GSK3B (glycogen synthase kinase 3 beta)
Diseases named in the same sentence as GSK3B in open-access papers (continued):
Sharing a sentence is not in itself a finding about the gene and the disease.
Peri-Implantitis (1 paper, 2020). An inflammatory process with loss of supporting bone in the tissues surrounding functioning DENTAL IMPLANTS. "We combined GSE33774 and GSE57631 and conducted WGCNA analysis, which showed that GSK3B appeared in key modules and had an important relationship with peri-implantitis." (PMID 33081707, 2020). "GSK3B and miR-1297 may have important significance in the immune microenvironment and pathogenesis of peri-implantitis." (PMID 33081707, 2020). "We found that GSK3B and miR-1297 may have important significance in the immune microenvironment and pathogenesis of peri-implantitis, which needs to be further proved by later experiments." (PMID 33081707, 2020). "In order to better detect the immune microenvironment of peri-implantitis, the CIBERSORT was used to evaluate the content of immune cells in normal tissues and peri-implantitis, and Pearson correlation was calculated between the gene expression level of GSK3B and 22 immune cells in peri-implantitis." (PMID 33081707, 2020).
pigmentation diseases (1 paper, 2022). "Taken together, these findings suggest that the regulation of melanogenesis by imperatorin can be mediated by signaling pathways involving PKA/CREB, ERK, AKT, and GSK3β/β-catenin and that imperatorin could prevent the pathogenesis of pigmentation diseases when used as a topical agent." (PMID 36235048, 2022).
Polyuria (1 paper, 2023). An increased rate of urine production. "A molecular-genetic analysis revealed an association of polyuria with glycogen synthase kinase-3beta (GSK-3β) gene polymorphism, which corresponds to the role of this enzyme in the regulation of urinary concentrating ability." (PMID 36678571, 2023).
pressure ulcer (1 paper, 2016). "The aim of the study was to explore the role of endoplasmic reticulum (ER) stress and Akt/GSK3β signaling in pressure ulcers." (PMID 26927073, 2016). "Taken together, we suggest that the molecular mechanisms of ER stress and the Akt/GSK3β signal pathway contribute to DTI of pressure ulcers." (PMID 26927073, 2016). "In the present study, we evaluated the changes in ER stress and the Akt/GSK-3β pathway in pressure-I/R injury-induced DTI in a pressure ulcer rat model." (PMID 26927073, 2016). "The present study was conducted to investigate whether pressure combined with I/R injury in a pressure ulcer could inhibit the phosphorylation of Akt and the downstream target GSK3β via inhibiting Akt activity." (PMID 26927073, 2016).
proliferative vitreoretinopathy (1 paper, 2025). Vitreoretinal membrane shrinkage or contraction secondary to the proliferation of primarily retinal pigment epithelial cells and glial cells, particularly fibrous astrocytes, followed by membrane formation. "The Akt/mTOR pathway is implicated in TGF‐β‐promoted pericyte‐myofibroblast transition subretinal fibrosis, and suppressed GSK3β expression and activated PI3K/Akt signaling have been observed in proliferative vitreoretinopathy models." (PMID 41147690, 2025).
prune belly syndrome (1 paper, 2018). "For example, Wntlss and β-catenin knockout manifesting in Prune belly syndrome and Wnt/β-catenin, Gsk-3b, Lrp5 and Lrp6 knockout causing ectopia cordis." (PMID 29483576, 2018).
psychostimulant addiction (1 paper, 2020). "The activity of GSK3β in the NAc core mediates the initiation and expression of methamphetamine-induced locomotor sensitization, suggesting that GSK3β may be a potential target for the treatment of psychostimulant addiction." (PMID 32694984, 2020).
R6 (1 paper, 2015). "A study of symptomatic R6/1 animals demonstrated that they had increased levels of inhibitory phosphorylation of GSK3β, suggesting the decreased activity of this molecule in the HD R6/1 model." (PMID 26092128, 2015).
radiation-induced dermatitis (1 paper, 2016). "The GSK3β rs3755557 polymorphism was significantly correlated with the acute grade 3–4 radiation-induced dermatitis in the allelic model (OR = 2.34, 95% CI = 1.05 – 5.21, P = 0.033)." (PMID 27769064, 2016). "Moreover, the A allele of GSK3β rs3755557 was also correlated to increased risk of grade 3–4 radiation-induced dermatitis compared with T allele (OR = 2.34, P = 0.033) in our study." (PMID 27769064, 2016).
rectal tumors (1 paper, 2023). "Previous studies have suggested that the MEN1 gene and PI3-K/AKT, Raf/MEK/ERK, Notch, GSK-3β and other signaling pathways may be involved in the occurrence and metastasis of multiple rectal tumors." (PMID 37264328, 2023).
red cell aplasia (1 paper, 2025). "The enrichment results in C5 sets revealed that GSK-3β may be related to abnormal erythrocyte adenosine deaminase activity, pure red cell aplasia, and erythroid hypoplasia." (PMID 41321870, 2025).
renal cystic disease (1 paper, 2022). "Additional studies are needed to delineate the interactions between CaMK4, GSK3β, and mTOR in the setting of renal cystic disease." (PMID 36002021, 2022).
renal dysfunction (1 paper, 2014). "Thus, it is possible that modulation of AKT/GSK3β/SMAD3 by AS101 which leads to attenuation in collagen expression plays a protective role against the development of renal dysfunction." (PMID 25474550, 2014).
respiratory infections (1 paper, 2021). "Finally, these findings might be relevant for other respiratory infections, including those caused by coronaviruses, where the aerosol delivery of molecules tuning autophagy and mTOR/GSK-3β axis might exert a therapeutic effect." (PMID 33936070, 2021).
retinal (1 paper, 2018). "We demonstrate for the first time that tau hyperphosphorylation via GSK3β activation causes vision deficits and synapse loss of RGCs in HFD-induced DR, which precedes retinal microvasculopathy and RGCs apoptosis." (PMID 30466464, 2018).
retinoblastoma (1 paper, 2023). A malignant tumor that originates in the nuclear layer of the retina. "A recent study indicated that MEG3 promoted β-catenin degradation via GSK-3β, which in turn inactivated the Wnt pathway and ultimately inhibited the invasion and metastasis of retinoblastoma cells." (PMID 36851033, 2023). "The inhibition of GSK-3β by its shRNA significantly reduced the role of MEG3 in regulating β-catenin and in promoting the invasion of retinoblastoma cells, suggesting that the GSK-3β protein is an important intermediator for the MEG3 functions." (PMID 36851033, 2023).
rhabdomyolysis (1 paper, 2023). Necrosis or disintegration of skeletal muscle often followed by myoglobinuria. "Altogether, those findings uphold the efficacy of GSK3β inhibitors in the management of rhabdomyolysis-associated AKI through their anti-apoptotic effects." (PMID 36795689, 2023). "Renal protein expression of GSK3β was attenuated in Gly+Li group, suggesting that inhibition of GSK3β may contribute to improve renal outcomes after rhabdomyolysis-associated AKI." (PMID 36795689, 2023).
rosacea (1 paper, 2025). A chronic erythematous skin disorder that affects the face. "Notably, proteins commonly implicated in neurodegeneration were increased in rosacea, including α-synuclein (SNCA), HSPA8, and GSK3B, while protein-level pathway enrichment flagged AD- and PD-related pathways." (PMID 41465136, 2025). "In rosacea, proteomic and transcriptomic investigations have revealed enrichment of neurodegeneration-related proteins such as SNCA, GSK3B, and HSPA8, as well as regulatory hubs including PPARG, STAT4, and RORA, which converge on NF-κB, IL-17, and TNF signaling pathways." (PMID 41465136, 2025).
SARS-CoV infections (1 paper, 2022). "It was found that 45.87% of the associated genes (CASP3, CASP9, MAPK1, MAPK3, XIAP) contributed to cytochrome C-mediated apoptotic response and 3.67% of the associated genes (BECN1, FXYD2, GSK3B, HSP90AA1, ITGB1, MAP1LC3B) contributed to SARS-CoV infections." (PMID 36164436, 2022).
scrapie (1 paper, 2010). A fatal disease of the nervous system in sheep and goats, characterized by pruritus, debility, and locomotor incoordination. "Additionally, it showed higher CDK5, but lower GSK3β transcriptional and expressive levels in the brains of scrapie-infected animals." (PMID 20356412, 2010). "In this study, we have firstly described that the cerebral level of GSK3β declines and that of CDK5 increases during scrapie pathogenicity." (PMID 20356412, 2010). "In parallel, the expression and transcription of GSK3β were depressed, while those of CDK5 were increased in the brains of scrapie-infected animals." (PMID 20356412, 2010).
serous carcinomas (1 paper, 2012). "Increased expression of GSK3B was associated with a favourable prognosis in our study, which is consistent with a report of higher GSK3B mRNA expression associated with better survival in ovarian high-grade serous carcinomas." (PMID 22970250, 2012).
Shock (1 paper, 2015). The state in which profound and widespread reduction of effective tissue perfusion leads first to reversible, and then if prolonged, to irreversible cellular injury. "We found the lung from rats with endotoxic shock exhibited significant decreases in the levels of Wnt3a, Fzd1, Dsh1, phosphorylated GSK-3β at Ser9, total β-catenin, and nuclear β-catenin when compared with the Control group." (PMID 26218875, 2015).
Skeletal muscle atrophy (1 paper, 2020). The presence of skeletal muscular atrophy (which is also known as amyotrophy). "A kinase-inactive form of GSK-3β and pharmacological inhibition of GSK-3β induce hypertrophy and have been applied as interventions for skeletal muscle atrophy." (PMID 32937135, 2020).
social anxiety disorder (1 paper, 2024). "The loss of miR-182-5p, in comparison, effectively improved impaired neurogenesis, prevented the decreased expression of Akt/GSK3β/CREB signal pathway, and relieved the immobility time, amount of sugar water consumed, and social anxiety disorder in these CSDS mice." (PMID 38038373, 2024).
TAFRO syndrome (1 paper, 2025). "Additionally, glycogen synthase kinase 3β (GSK3β) and CC chemokine receptor 6 (CCR6) have been identified as upstream positive regulators of TAFRO syndrome, which could serve as both diagnostic markers and therapeutic targets for TAFRO syndrome." (PMID 40248702, 2025).
Telangiectasia (1 paper, 2016). Telangiectasias refer to small dilated blood vessels located near the surface of the skin or mucous membranes, measuring between 0.5 and 1 millimeter in diameter. "Here we show that phosphorylation of GSK3β on Ser389 by p38 MAPK (mitogen-activated protein kinase) is induced selectively by DSBs through ATM (ataxia telangiectasia mutated) as a unique mechanism to attenuate the activity of nuclear GSK3β and promote survival of cells undergoing DSBs." (PMID 26822034, 2016).
teratocarcinoma (1 paper, 2016). A germ cell tumor characterized by the presence of an embryonal carcinoma component and a teratoma component. "Lastly, given that PrE-like differentiation in F9 teratocarcinoma cells was shown to require p38-Mapk14/11 mediated inhibition of Gsk3β function, we tested if our observed uncommitted ICM phenotype could be rescued by direct pharmacological inhibition of Gsk3β itself and found that it could not." (PMID 27605380, 2016).
teratoma (1 paper, 2011). A non-seminomatous germ cell tumor characterized by the presence of various tissues which correspond to the different germinal layers (endoderm, mesoderm, and ectoderm). "In contrast, mESCs cultured in CDSF with Bmp4 or the Gsk3β inhibitor maintained Oct3/4 expression, increased the number of cell doublings and formed teratomas in 17% or 67% of transplantations by 7 months, respectively." (PMID 21731714, 2011). "In contrast, our RT-PCR results showed that mESCs cultured under CDSF conditions with the Gsk3β inhibitor failed to significantly upregulate transcription of Eras and c-Myc but efficiently developed into teratomas." (PMID 21731714, 2011).
testicular teratoma (1 paper, 2022). "To determine the effect of the MAP3K1R186G variant on kinase and ovarian-specific pathways, we evaluated phosphorylation levels of p38 and GSK3β as well as activation of the Wnt4/β-catenin pathway in the testicular teratoma cells (NT2/D1) and ovary-derived granular cells (KGN)." (PMID 35309143, 2022).
thymic lymphomas (1 paper, 2024). "The PRL2-deficient thymic lymphomas had reduced pS9 in GSK3β, which supports reduced proliferation observed in tumors derived from these mice (61% reduction, P = 0.0271)." (PMID 38047587, 2024).
tuberculosis (1 paper, 2026). A chronic, recurrent infection caused by the bacterium Mycobacterium tuberculosis. "By targeting the GSK3β/HIF-1α axis, this study presents a potential strategy for managing other intracellular infections, including tuberculosis and chronic viral diseases, where hypoxia signaling is critical." (PMID 41509906, 2026).
tuberous sclerosis (1 paper, 2017). Hereditary disease characterized by seizures, intellectual disability, developmental delay, and skin and ocular lesions. "Tuberous sclerosis complex (TSC) is a rare genetic disorder that is characterized by an increase in protein synthesis and a decrease in GSK3β activity." (PMID 28646232, 2017). "Inhibition of ERK restores both GSK3β activity and levels of protein synthesis in Tsc2−/− cells, thus identifying ERK as a candidate therapeutic target for the treatment of tuberous sclerosis." (PMID 28646232, 2017). "In addition, the finding that ERK regulates protein synthesis via modulation of GSK3β activity in an Akt/mTORC1-independent manner provides a new regulatory pathway that could be exploited for combinatorial therapeutic interventions in tuberous sclerosis." (PMID 28646232, 2017).
tularemia (1 paper, 2015). Tularemia is an infection caused by the bacterium Francisella tularensis. "GSK-3β is a serine/threonine protein kinase that has been shown recently to play a key role during the inflammatory response induced by various pathogenic bacteria, such as Francisella tularensis, the causative agent of highly virulent tularemia, Burkholderia pseudomallei and group A streptococcus." (PMID 25385175, 2015).
uterine carcinosarcoma (1 paper, 2013). A usually aggressive malignant neoplasm arising from the uterine corpus and less often the cervix. "The activation of PI3K/Akt signaling has been demonstrated to stimulate Slug expression via GSK-3β/β-catenin signaling and to subsequently down-regulate E-cadherin in uterine carcinosarcomas and normal hepatocytes." (PMID 23554977, 2013).
vitiligo (1 paper, 2025). Generalized well circumscribed patches of leukoderma that are generally distributed over symmetric body locations and is due to autoimmune destruction of melanocytes. "Our findings suggest that IFN-γ activates GSK3β to inhibit β-catenin activity in follicular cells and skin, inducing vitiligo-like pigment loss in models." (PMID 40790580, 2025).
ZIKV infection (1 paper, 2022). "Thus, ZIKV infection of neurons sets up the conditions for a PKR-dependent activation of GSK3B and the subsequent induction of pTau, potentially linking IFNB response to ZIKV-induced pTau." (PMID 36539803, 2022). "Preliminary results obtained in vitro show that ZIKV infection indeed leads to a significant increase of the active form of kinase GSK3B in PCNs but not MEFs." (PMID 36539803, 2022).
tumor (1,052 papers, 2003 to 2026). "A literature review revealed that MACF1 significantly induced PI3K/AKT and GSK3β activities and was closely associated with tumor metastasis." (PMID 40084246, 2025). "Concurrently, PI3K/AKT-phosphorylated Glycogen Synthase Kinase-3 Beta promotes tumor proliferation associated with multidrug resistance and is often considered a critical node regulating cancer multidrug resistance." (PMID 41227351, 2025). "This study was designed to analyze the expression and clinical significance of GSK-3β and investigate its association with tumor stemness–related and immune-related genes." (PMID 41321870, 2025). "SLIT2 slows growth, while ROBO1 promotes it, by regulating the TGF-β1/GSK3-β/β-catenin signaling pathway in tumor cells and tumor-associated macrophages (TAMs)." (PMID 41217667, 2025). "The AKT/GSK3β/β-catenin pathway has been implicated in tumor proliferation, invasion, metastasis, stemness, and drug resistance, including LR." (PMID 40336047, 2025). "In orthotopic and subcutaneous mouse models, GSK3β inhibitors in combination with Olaparib substantially reduced tumor growth in both BRCA1-proficient and -deficient settings." (PMID 41243967, 2025). "In TNBC, 24 GSK-3β-associated genes linked to tumor stemness and immune response were identified, all of which were downregulated in the high GSK-3β expression group." (PMID 41321870, 2025). "GSK-3β, a serine/threonine kinase, plays dual roles in cancer, with its activation often associated with tumor suppression." (PMID 40643495, 2025). "Survival analysis, differential gene expression, and gene set enrichment analysis (GSEA) were performed to explore associations between GSK-3β and tumor stemness, immune response, and clinical outcomes in TNBC." (PMID 41321870, 2025). "Wnt–β-catenin pathway dysregulation is often caused by mutations in various pathway components, particularly mutations or silencing of Wnt tumor suppressor genes, Axin1/2 mutations, and GSK3β loss." (PMID 40818609, 2025). "Specifically, PPIs were found to promote PD‐L1 expression on the membranes of various malignant cells by inducing GSK3β phosphorylation, thereby facilitating tumor progression and resulting in an increased risk of immunosuppression." (PMID 38752436, 2024). "Specifically, a preclinical study showed that inhibition of miRNA-26a prevented β-catenin activation and transcription of its target genes and slowed the rate of tumor growth, an effect caused by this microRNA blocking the GSK3β mRNA." (PMID 37190050, 2023). "FBXW7 recognizes hypoxia-induced phosphorylated HIF-1α for degradation via GSK3β, thereby the loss of FBXW7 or GSK3β results in increased hypoxia-induced stimulation of angiogenesis and contributes to tumor growth." (PMID 37176148, 2023). "Since GSK3β activity is linked to Bmi1, inhibition of GSK3β activity by lithium triggered tumor cell differentiation, increased apoptosis, the disintegration of tumor spheroids, and decreased clonogenicity." (PMID 36836894, 2023). "It is also beginning to emerge that GSK-3β is mutated in approximately 1–4% of several tumor types (e.g., uterine endometrioid carcinoma, skin cancer, uterine neoplasms, melanoma, non-small-cell lung cancer, and cervical squamous cell carcinoma)." (PMID 35681507, 2022). "The effects of GSK-3β inhibition on tumour invasion, susceptibility to gemcitabine, MMP-2 expression and FAK phosphorylation were observed in vitro as well as in tumour animal models." (PMID 36430630, 2022). "Dys-regulation of GSK3β is implicated in many different pathologies, including neurodegenerative disorders as well as many different tumour types." (PMID 34739494, 2021). "This was slightly lower in the Gsk3b cKO, with 40% of mice surviving at day 50; here increased survival was associated with diminished tumor growth and the eventual eradication of tumor was apparent within 15–20 days post-tumor challenge." (PMID 34142056, 2021).